ITGA5 (integrin subunit alpha 5)
Diseases named in the same sentence as ITGA5 in open-access papers (continued):
Sharing a sentence is not in itself a finding about the gene and the disease.
oral squamous cell carcinoma (5 papers, 2020 to 2023). "ITGA5 promoted cell proliferative, migrative and invasive abilities in oral squamous cell carcinoma (OSCC) by regulating PI3K/AKT signaling pathway, thus promoting the malignant advancement of o OSCC." (PMID 36742137, 2023). "ITGA5 promotes proliferation, migration and invasion of oral squamous cell carcinoma cell lines through EMT (epithelial-mesenchymal transition)." (PMID 36267977, 2022). "Previous studies have shown ITGA5 could promote the proliferation, migration, and invasion of oral squamous cell carcinoma through activating the PI3K/AKT signaling pathway." (PMID 34573489, 2021). "In addition, previous findings showed that ITGA5 regulated PI3K/AKT signaling pathway in oral squamous cell carcinoma." (PMID 32955094, 2020). "Several previous studies have presented that ITGA5 could operate in certain diseases including bladder cancer, oral squamous cell carcinoma and gastric cancer via PI3K/AKT pathway." (PMID 32955094, 2020).
COVID-19 (4 papers, 2021 to 2024). A disease caused by infection with severe acute respiratory syndrome coronavirus 2. "The univariate Cox analysis highlighted that 7 genes (including MRC1, CP, ITGA5, SNCA, HARS1, ENPP1, and PLAU) were significantly (p < 0.05) associated with CHOL/COVID-19." (PMID 34176789, 2021). "A transcriptome profile analysis also showed the overexpression of ITGA5 in lung samples from COVID-19 patients." (PMID 34176789, 2021). "As per the independent prognostic and survival analyses, few of the important differentially expressed genes, including MRC1, CP, ITGA5, SNCA, HARS1, ENPP1, and PLAU may function as potent biomarkers for screening and characterizing different stages of CHOL patients with COVID-19." (PMID 34176789, 2021).
epidermoid carcinoma (4 papers, 2016 to 2025). "Our results echo another study that ITGA5 simultaneously controlled these two critical signaling cascades in epidermoid carcinoma cells." (PMID 27050274, 2016). "Notably, previous research has established PLAU and ITGA5 as critical biomarkers for various types of squamous cell carcinoma." (PMID 37510272, 2023). "ITGA5 promotes EMT in squamous cell carcinoma cells, and knockdown of NONO led to reduced expression of ITGA5 in PCa." (PMID 40509555, 2025).
pancreatic adenocarcinoma (4 papers, 2018 to 2023). "Our results also show that high expression of the fibronectin receptor subunits ITGA5 and ITGB1 correlates with poor disease-free survival in patients with pancreatic adenocarcinoma." (PMID 37563605, 2023). "For example, cholangiocarcinoma (CHOL) overexpresses a large variety of subunits (e.g. ITGAV, ITGA1, ITGA4, ITGA5, ITGA11, ITGB1, ITGB2, ITGB6), whereas, the equally deadly pancreatic adenocarcinoma (PAAD) overexpresses a very limited set of integrins, including ITGA6 and ITGB4." (PMID 30046394, 2018).
Stroke (4 papers, 2017 to 2024). Sudden impairment of blood flow to a part of the brain due to occlusion or rupture of an artery to the brain. "AZ_628, which screened from CMap analysis, was found to have lower binding energy with Mmp12, Lgals3, Fam20c, Capg, Pkm2, Sdc4, and Itga5 in microglia subcluster 2 and maybe a therapeutic agent for the poor development of microglia subcluster 2 after stroke." (PMID 38067435, 2023). "Therefore, the up-regulation of Itga5 in endothelia cells plays a deleterious role in stroke pathophysiology." (PMID 28724924, 2017). "Similarly, genes involved in integrin cell surface interactions including Itga10, Itgb3, Vcam1, Itgb1, Itgae, Itgb7, Itga1, Itga5, Icam1, Itgb2, Pecam1, and Icam2 were depleted in male MMP-3 KO stroke brains." (PMID 39000490, 2024). "However, some genes are unresolved by 7 days post-stroke comprising primarily cell adhesion and ECM-endothelial interaction molecules such as ITGB2, ITGA5 indicating persistent disruption of the BBB but also glutamatergic pathways as a hint for ongoing cytotoxicity." (PMID 32300291, 2020).
atopic dermatitis (3 papers, 2015 to 2024). "In support of this, deficiency of POSTN or inhibition of α5 integrin (ITGA5) prevented development or progression of skin inflammation in an atopic dermatitis mouse model." (PMID 25678896, 2015). "CHI3L1/ITGA5 axis was related to treating atopic dermatitis." (PMID 36742137, 2023).
cholangiocarcinoma (3 papers, 2018 to 2024). A carcinoma that arises from the intrahepatic biliary tree (intrahepatic cholangiocarcinoma) or from the junction, or adjacent to the junction, of the right and left hepatic ducts (hilar cholangiocarcinoma). "In terms of cancer types, ITGA10 and ITGA5 represented the most frequently amplified genes in cholangiocarcinoma (CHOL), whereas other integrin genes were rarely amplified." (PMID 39436262, 2024).
diabetes (3 papers, 2018 to 2024). "ITGA5, a hub gene identified in this study, has also been reported to engage in pathological angiogenesis and vascular remodeling and diabetes-related vascular inflammation." (PMID 38297356, 2024). "We did not observe diabetes-associated changes in gene expression of cellular identity genes, such as Itga5, Ly6a (SCA1), and Thy1; however, diabetes was associated with changes in gene expression of ECM- and inflammation-related genes." (PMID 34944568, 2021). "The upregulation of certain mRNA isoforms of the ITGA5, TIMP1, ANXA2 and LITAF genes in HIGH pigs is relevant because these four genes have been implicated in human obesity and diabetes." (PMID 29444639, 2018).
esophageal cancer (3 papers, 2021 to 2022). A primary or metastatic malignant neoplasm involving the esophagus. "Studies on the cisplatin resistance of esophageal cancer revealed that ITGA5 causes increased DNA loss repair and antiapoptosis through the activation of the FAK/PI3K/AKT signaling pathway." (PMID 36193075, 2022). "MiR-30b-5p inhibits the migration and invasion of esophageal cancer by targeting ITGA5 and PDGFRb." (PMID 34819077, 2021).
laryngeal squamous cell carcinoma (3 papers, 2022 to 2025). A squamous cell carcinoma that arises from the larynx. "It has also been reported that ITGA5 expression is associated with lower overall survival and recurrence-free survival rates in laryngeal squamous cell carcinomas." (PMID 39857068, 2025).
Obesity (3 papers, 2013 to 2021). Accumulation of substantial excess body fat. "SP1 not only is located within ±1 Mb of obesity SNP rs1443512 (similar to ITGA5), but also has the highest differential expression percentage (63.6%)." (PMID 24455749, 2013). "This indicated that the adipose tissue of obese mice was often accompanied by fibrosis, and ITGA5 may be closely related to obesity and fibrosis." (PMID 34830238, 2021). "The increased levels of specific ITGA5, LITAF, TIMP1 and ANXA2 mRNA isoforms in HIGH pigs is consistent with reports indicating that the overexpression of these four genes is associated with obesity and metabolic disorders in humans." (PMID 29444639, 2018). "Moreover, ITGA5 is located within ±1 Mb of the obesity SNP, rs1443512." (PMID 24455749, 2013). "Using the same method, seven highly ranked genes (BAP1, GRB14, HSP90AB1, ITGA5, NCKAP5L, SP1, and TOMM5) within ±1 Mb of obesity SNPs were identified." (PMID 24455749, 2013).
osteosarcoma (3 papers, 2006 to 2022). A usually aggressive malignant bone-forming mesenchymal neoplasm, predominantly affecting adolescents and young adults. "ITGA5 was markedly downregulated in osteosarcoma tissues but upregulated in Ewing's sarcoma tissues compared to normal tissues." (PMID 35578666, 2022).
rheumatoid arthritis (3 papers, 2015 to 2025). A chronic, systemic autoimmune disorder characterized by inflammation in the synovial membranes and articular surfaces. "Apart from acting as a POSTN ligand (along with ITGA5), ITGB5 has also been implicated in rheumatoid arthritis, where it serves as a ligand for Cyr61." (PMID 25678896, 2015).
Arthritis (2 papers, 2025 to 2026). Inflammation of a joint. "Specifically, we assayed if these CD47Hi and CD47Lo sub-populations expressed ITGA5 and/or DPP4/CD26 as these markers have previously been associated with stromal progenitors and shown to play a role in the progression of arthritis." (PMID 41557734, 2026). "Recently, ITGA5+ synovial fibroblasts were shown to exacerbate inflammatory joint pathology in a collagen-induced arthritis model." (PMID 40563469, 2025).
asthma (2 papers, 2019 to 2026). "Elevated ITGA5 expression correlated positively with reduced lung function, asthma severity and higher levels of EMT regulators (Fibronectin, N-cadherin, Vimentin) and was functionally linked to anoikis resistance." (PMID 41772919, 2026). "This study reported that integrin α5 (ITGA5) was markedly upregulated in asthma patients, house dust mite (HDM)-sensitised asthma mice, and transforming growth factor beta 1 (TGF-β1)-induced in vitro EMT models." (PMID 41772919, 2026).
bone metastasis (2 papers, 2021 to 2022). Transfer of a neoplasm from its primary site to bones. "Kaplan–Meier survival analysis revealed that the risk of bone metastasis was significantly higher for patients with high ITGA5 levels (HR = 1.62, p = 0.024)." (PMID 33420367, 2021). "Specifically, we report that high ITGA5 levels in primary tumors were predictive of poor bone metastasis-free survival in two separate clinical data sets (HR = 1.36, p = 0.018 and HR = 1.62, p = 0.024)." (PMID 33420367, 2021). "ITGA5 was also predictive of poor bone metastasis-free survival in two separate clinical data sets (n = 855, HR = 1.36, p = 0.018 and n = 427, HR = 1.62, p = 0.024)." (PMID 33420367, 2021).
brain tumor (2 papers, 2021 to 2023). "To validate the significant in vitro functional effects of ITGA5 knockdown on brain tumor initiating capacity we xenografted HD-MB03-Re cells transduced with control and ITGA5-4 short hairpins and measured tumor burden and overall survival." (PMID 37430373, 2023). "As a member of the integrin family, ITGA5 has been shown to play a regulatory role in tumor cell proliferation, migration, invasion, ECM remodeling, angiogenesis, therapy evasion and modulating immune infiltration across multiple cancer types and models including other types of brain tumors." (PMID 37430373, 2023).
colon adenocarcinoma (2 papers, 2021). "Surprisingly, both targets of miR-148a allowed us to predict the overall survival in colon adenocarcinoma patients with a statistical significance: logrank test p was equal to 0.0133 and 0.0119 for ITGA5 and PRNP, respectively." (PMID 34135940, 2021).
fibrosis (2 papers, 2021 to 2024). the formation of excess fibrous connective tissue in an organ or tissue in a reparative or reactive process. "Specifically, we used mRNA expression of Krt8 (indicative of injury/repair), Krt5 (related to dysfunctional repair), Adamts4 (associated with fibrosis), and Itga5 (indicative of damage-responsive fibroblasts)." (PMID 39340037, 2024). "To further explore the effect of ITGA5 on adipocytes fibrosis, we constructed a fibrosis model by treating adipocytes with TGF-β, and then separately treated adipocytes with the ITGA5 overexpression vector and interference fragments." (PMID 34830238, 2021).
head and neck cancer (2 papers, 2025). A primary or metastatic malignant neoplasm affecting the head and neck. "Recent evidence shows that high expression of ITGA5 and ITGA6 in head and neck cancers is associated with increased infiltration of immunosuppressive cells, reflecting an exhausted tumor immune microenvironment." (PMID 41347085, 2025).
infarction (2 papers, 2021 to 2023). A localised pathological necrosis of tissue resulting from obstruction of the blood supply usually by a thrombus, an embolus, or vascular torsion. "Our scRNA-seq experiments identified a macrophage subpopulation with an angiogenic transcriptional profile that expands following infarction and expresses high levels of Itga5." (PMID 37985764, 2023). "Echocardiographic analysis showed that myeloid cell-specific ITGA5 deletion accentuated adverse remodeling after infarction, increasing LVEDV and LVESV, 28 days after coronary occlusion." (PMID 37985764, 2023). "Infarct macrophages exhibited marked induction of Itga5, Itgav and Itga6 that was first noted 3 days after infarction and further increased at the 7-day timepoint." (PMID 37985764, 2023). "Moreover, comparison of expression levels between infarcted and control hearts showed significant Itga5 upregulation in reparative macrophages following infarction (RMp, log2(Infarct/control)=0.54, padj=4.15E-0.6)." (PMID 37985764, 2023). "Myeloid cell-specific ITGA5 loss did not have a significant effect on post-infarction mortality in male or female mice (n = 33–35/group)." (PMID 37985764, 2023).
ischemic stroke (2 papers, 2017 to 2025). A stroke disorder caused by obstruction of blood flow to the brain, due to thrombotic (local blood clot formation) or embolic (due to a blood clot or other material traveling from another site) event. "Therefore, a local inhibition of Itga5 of both brain endothelia cells and cortical neurons at acute or sub-acute phase after ischemic stroke might be a promising therapeutic approach for further testing." (PMID 28724924, 2017). "For example, in both in vitro OGD/R and in vivo ischemic stroke model (MCAO/R) models, integrin-alpha-5 (Itga5) and receptor tyrosine kinase (ErbB4) were up-regulated or down-regulated after reperfusion, respectively." (PMID 28724924, 2017). "Because ANGPT2 regulates angiogenesis through TEK and integrin signaling, and promotes neuroprotection in a model of ischemic stroke, the ANGPT2–TEK/ITGA5:ITGB1 signaling axis from EC:Exc3/Exc5 to fibroblasts (EC:Fib) likely represents a resilience-linked angiogenic support mechanism." (PMID 41035073, 2025).
mesothelioma (2 papers, 2021 to 2023). A usually malignant and aggressive neoplasm of the mesothelium which is often associated with exposure to asbestos. "CD26, a cancer stem cell marker of malignant mesothelioma, has been shown to associate with the integrin α5β1 (or ITGA5, a novel interactor of the MPM gene, FGFR2) and promote cell migration and invasion in mesothelioma cells." (PMID 33916178, 2021).
metastasis (2 papers, 2021). The spread or migration of cancer cells from one part of the body (where they first appeared) to another. "Additionally, it was observed that the overexpression of integrin ITGA5 was associated with lymph node metastasis and tumor size growth in esophageal squamous cell carcinoma." (PMID 34680783, 2021).
muscular dystrophy (2 papers, 2016 to 2019). Muscular dystrophy (MD) refers to a group of more than 30 genetic diseases characterized by progressive weakness and degeneration of the skeletal muscles that control movement. "Muscular dystrophy was observed in patients with ITGA5 or ITGA7 mutations." (PMID 31623094, 2019). "Notably, the expression of ITGA5 and ITGA6 has been linked to active regeneration of skeletal muscle in muscular dystrophy, and both of these integrins were expressed only in the mutant samples (with the intensity for both components being between 1 × 106 and 1 × 108)." (PMID 27099343, 2016).
oral cancer (2 papers, 2022 to 2023). "Furthermore, ITGA5 promotes the development, migration, and invasion of cells that undergo an epithelial-mesenchymal transition in oral cancer." (PMID 37822877, 2023).
adrenocortical carcinoma (1 paper, 2022). "The result of the Kaplan–Meier analysis demonstrated that ITGA5 was confirmed as a significant protective factor only in adrenocortical carcinoma (ACC)." (PMID 35371978, 2022).
Aortic dissection (1 paper, 2021). Aortic dissection refers to a tear in the intimal layer of the aorta causing a separation between the intima and the medial layers of the aorta. "In addition, ITGA3 and ITGA5 were identified as new biomarkers for the onset of acute aortic dissection." (PMID 33953793, 2021).
atrial fibrillation (1 paper, 2024). A disorder characterized by an electrocardiographic finding of a supraventricular arrhythmia characterized by the replacement of consistent P waves by rapid oscillations or fibrillatory waves that vary in size, shape and timing and are accompanied by an irregular ventricular response. "In the adult heart, ITGA5 has been found to be upregulated in the atrial tissues of patients with atrial fibrillation, whereas epicardial secreted fibronectin has been identified as a source of fibroblasts through the EMT process." (PMID 39200271, 2024).
autism (1 paper, 2024). Persistent deficits in social interaction and communication and interaction as well as a markedly restricted repertoire of activity and interest as well as repetitive patterns of behavior. "In contrast, Col1 and Itga5 (which we both found to be under-expressed DEGs) have been described as over-expressed in an adult rat model of autism." (PMID 38123724, 2024).
cancers of the larynx (1 paper, 2019). "The percentage of ITGA5-positive samples was 10% in cancers of the oral cavity, 16% in cancers of the oropharynx, and 19% in cancers of the larynx." (PMID 31661833, 2019).
carcinoid (1 paper, 2021). "The expression of COL1A2, COL3A1, COL5A2, ITGA5, and ITGB1 in SCLC, LCNEC, and typical carcinoid samples in the GSE1037 profile, as compared with normal samples, were determined using a GEO2R online analyzer (log FC>2 and adjusted P<0.05) and then compared to the data from our cohort." (PMID 34458147, 2021).
Chlamydia infection (1 paper, 2018). "When α5 integrin subunits were masked by a specific blocking antibody or ITGA5 gene expression was silenced, Chlamydia infection was significantly reduced." (PMID 30459737, 2018).
colorectal adenocarcinoma (1 paper, 2019). The most common type of colorectal carcinoma. "Consistently, ITGA5 was significantly correlated with FN (P < 0.0001; r = 0.7958, Pearson’s correlation) in 24 freshly isolated colorectal adenocarcinoma samples by assessing the mRNA expression using qPCR." (PMID 31600854, 2019). "We observed that most tumor tissue samples from patients with colorectal adenocarcinoma (21/24; 87.5%) showed elevated levels of ITGA5 compared with the corresponding adjacent normal tissue samples (P = 0.0003)." (PMID 31600854, 2019). "Characteristics of 517 colorectal adenocarcinoma cases according to ITGA5 expression levels in TCGA cohort." (PMID 31600854, 2019). "Analysis of the RNA‐Seq data of the Cancer Genome Atlas cohort revealed that high expression of ITGA5 (α5 integrin subunit) was correlated with poor overall survival in colorectal adenocarcinoma, which was further confirmed by immunohistochemistry in an independent cohort of 355 patients." (PMID 31600854, 2019). "Thus we analyzed the correlation between the expression levels of ITGA5 and CAF‐related marker genes in 24 freshly isolated colorectal adenocarcinoma samples by assessing the mRNA expression using qPCR." (PMID 31600854, 2019).
disc degeneration (1 paper, 2025). "Therefore, we do not recommend secondary viral injection in IVDD animals to explore therapeutic effects of SPP1 or ITGa5 knockdown, which is contrary to our intention to explore therapeutic strategies for disc degeneration." (PMID 39721032, 2025).
endometriosis (1 paper, 2020). The growth of functional endometrial tissue in anatomic sites outside the uterine body. "Khorram and Lessey associated decreased expression levels of ITGA5/ITGB3 integrin during the WOI in endometriosis women with an unfavourable environment for embryo implantation." (PMID 32474803, 2020).